SMAD3 (SMAD family member 3)
Diseases named in the same sentence as SMAD3 in open-access papers (continued):
Sharing a sentence is not in itself a finding about the gene and the disease.
renal fibrosis (continued). "Indeed, the reduction of Smad3-mediated renal fibrosis was observed in mouse models of chronic kidney diseases overexpressing miR-29 and miR-200, or showing decreased expression of miR-21 and miR-192." (PMID 37760798, 2023). "It is further important to understand the profibrotic role of Smad3 in renal fibrosis." (PMID 37559381, 2023). "Additionally, TGF-β is reported to regulate the expression of several miRNAs including miR-21 upregulation, suggesting its role in TGF-β induced renal fibrosis through TGF-β/Smad3 signaling." (PMID 38201260, 2023). "SSR could contribute to renal protection by up-regulating SIRT1/Smad3 deacetylation pathway and attenuating renal fibrosis in 5/6 nephrectomy model of CKD." (PMID 35795148, 2022). "Therefore, deletion of Smad3 or overexpression of Smad7 protects kidney from Smad3-mediated renal fibrosis and NFκB-driven renal inflammation under diabetic and hypertensive conditions 3, 7-11." (PMID 36147472, 2022). "In addition, poricoic acid A can also inhibit renal fibrosis by activating the AMPK signaling pathway to inhibit TGF-β1/Smad3 pathway-mediated deposition of ECM and activation of myofibroblasts." (PMID 35978370, 2022). "Using Smad3 inhibitors, such as a combination of asiatic acid and naringenin, could reduce the activation of TGF-β/Smad3 signaling and inhibit renal fibrosis." (PMID 35990655, 2022). "Reports indicate that advanced glycation end products (AGEs), a by-product of hyperglycemia-induced EndMT through receptor for AGE (RAGE)-Smad3 cross-talk and inhibiting such pathway retarded the early development of renal fibrosis in STZ-induced diabetic mice." (PMID 35392173, 2022). "Additionally, nintedanib suppressed PDGFRβ, FGFR1, FGFR2, and VEGFR2 phosphorylation and blocked the expressions of STAT3, NF-κB, and Smad3 to diminish macrophage infiltration, thereby ultimately exerting anti-renal fibrosis effects." (PMID 35250597, 2022). "In a mouse model of unilateral ureteral obstruction, CDK9 could also conjugate with Smad3 and Smad4 to form a complex to promote renal fibrosis." (PMID 36313366, 2022). "Smad3 can also regulate Smad7 to play a role in renal fibrosis." (PMID 35541902, 2022). "Mechanically, we uncovered that the combinational treatment with AA and NG produced a better effect on rebalancing Smad3/Smad7 signaling in the diabetic kidney, thereby resulting in more effectively inhibiting Smad3-mediated renal fibrosis and NF-κB-driven renal inflammation." (PMID 36147472, 2022). "TGF-β/Smad3 is the main pathway of renal fibrosis, and Smad7 could block the phosphorylation of Smad3, thereby limiting the effect of TGF-β." (PMID 35145414, 2022). "However, in Smad3 knockout mice, Ang-II-induced renal fibrosis and NF-κB-driven renal inflammation was significantly lower compared to the wild-type, highlighting functions of Ang II in promoting TGF-β cell signals." (PMID 35237156, 2022). "As Smad3 is a key mediator of renal fibrosis 51, it is highly possible that after SARS-CoV-2 infection, intracellular release of SARS-CoV-2 N protein can bind and activate TGF-β/Smad3 signaling to induce the cell death pathway to trigger renal inflammation and “cytokine storm”, resulting in AKI." (PMID 35541902, 2022). "MiR-192 is also a downstream mediator of TGF-β/Smad3 in renal fibrosis." (PMID 35541902, 2022). "A recent study has shown that knockdown of CDK9 and a CDK9 inhibitor (LDC000067) could remarkably ameliorate renal fibrosis by blocking the phosphorylation of the Smad3 linker (Thr179)." (PMID 36313366, 2022). "In a CKD rat model, treatment with deferasirox (DFX), could mitigate renal fibrosis by inhibiting TGF-β1/Smad3, inflammation, and oxidative stress pathways." (PMID 35050181, 2022). "TGF-β1/Smad3 is a key signaling pathway in pulmonary, hepatic, and renal fibrosis." (PMID 36474625, 2022).
renal fibrosis (continued). "Furthermore, the antifibrotic effect shown in Smad3−/− chimeric mice suggests that BMDMs contribute to the development of renal fibrosis via MMT, while the process is mediated by TGF-β/Smad3 signaling." (PMID 35990655, 2022). "Specifically, HIF-1α could bind to Smad3, upregulate the level of fibrosis-related proteins, and promote renal fibrosis." (PMID 35957825, 2022). "Previous studies have shown that signaling factors such as JAK2/STAT3, Smad3, and Myd88 play a regulatory role in renal fibrosis, and β-elemene is a plant-derived sesquiterpenoid organic compound that has been shown to have anti-inflammatory, anti-cancer, and immunomodulatory effects." (PMID 35628363, 2022). "In this study, we found that β-elemene attenuated renal interstitial fibrosis and down-regulated ECM protein expression in UUO mice by inhibiting STAT3 and Smad3 signaling via suppressing MyD88 expression, suggesting that β-elemene is effective in the treatment of renal fibrosis." (PMID 35628363, 2022). "In contrast, in UUO models, blocking DOT1L with EPZ5676 alleviates renal fibrosis by inhibiting multiple fibrosis pathways (including Smad3, EGFR, PDGFR and NF-κB pathway), up-regulating the expressions of renal protective factors such as PTEN, Klotho and Smad7,2." (PMID 35559246, 2022). "In conclusion, we identify a safe dosage and optimal combination ratio of AANG for preventive treatment of T2D and T2DN by effectively rebalancing Smad3/Smad7 signaling, thereby inhibiting TGF-β/Smad3-mediated renal fibrosis and NF-κB-driven renal inflammation." (PMID 36147472, 2022). "In addition, Erbb4-IR can also target Smad7, and specific silencing of Erbb4-IR expression up-regulates Smad7 in the kidneys, thereby attenuating TGF-β1/Smad3-induced renal fibrosis in vivo and in vitro." (PMID 36299256, 2022). "Moreover, current studies have shown that Smad3 mediates renal fibrosis by downregulating miR-29 and miR-200, and upregulating miR-21 and miR-192." (PMID 34112221, 2021). "Because the TGF-β1/ Smad3 pathway was blocked, the progression of renal fibrosis could be managed by those herbal drugs." (PMID 34439425, 2021). "Latent TGF-β1 may protect kidneys from TGF-β1/Smad3-mediated renal fibrosis and NF-κB-driven renal inflammation in diabetes through inhibiting Arkadia-mediated Smad7 ubiquitin degradation." (PMID 34512167, 2021). "And RES could significantly reduce the Smad3 acetylation levels in the remnant kidney of 5/6 nephrectomized rodents or in cultured cells following TGF-β1 treatment–induced renal fibrosis." (PMID 34177571, 2021). "Smad3 mediates renal fibrosis by promoting CRP-induced TGF-β1/Smad3 signalling." (PMID 34671208, 2021). "Our results suggest that the role of TGFβ in renal fibrosis could be addressed through Smad proteins, in which Smad3 induces ECM synthesis, but its deletion inhibits tubulointerstitial fibrosis." (PMID 34769064, 2021). "In this process, Smad3 plays a major role in the development of renal fibrosis." (PMID 34327204, 2021). "CRP may promote CD32b- NF-κB signaling to mediate renal inflammation and may enhance renal fibrosis in T2DN via CD32b-Smad3-mTOR signaling." (PMID 34603198, 2021). "Taken together these data strongly support the case that targeting SGLT2 could also inhibit the glucose-TGF-β1/ERK/Smad3 signalling cascade and subsequent key elements of renal fibrosis in our PTECs." (PMID 34003249, 2021). "TGF-β/Smad3-dependent lncRNAs in renal fibrosis and inflammation." (PMID 34054586, 2021). "On this basis, an alternative explanation for our findings is that JMJD3 inhibition-mediated upregulation of TGFβ1 and activation of Smad3 strengthens activation of Notch signaling, which in turn, further activates TGFβ1 signaling, creating a vicious circle that accelerates renal fibrosis." (PMID 33456568, 2021). "In the mouse model of UUO, deletion of Smad3 significantly reduces renal fibrosis." (PMID 34360646, 2021).
renal fibrosis (continued). "In addition, inhibition of Smad3 using specific inhibitors (SIS3) can also suppress renal fibrosis 24-27." (PMID 34671208, 2021). "Smad3 exhibited an obvious deposition of collagen, contributing to the development of renal fibrosis in db/db mice, whereas this process could be inhibited by Smad3 knockout." (PMID 34327204, 2021). "It is now clear that Smad7 is an integrated inhibitor not only for inhibiting TGF-β/Smad3-mediated renal fibrosis by competing with the R-Smad binding to the TβRI 24 but also for suppressing IκBα ng NF-κB-driven renal inflammation by inducing, an NF-κB inhibitor 25,26." (PMID 34512167, 2021). "Increased acetylated-Smad3 (Ac-Smad3) protein expression is associated with increased cardiac fibrosis, and RES was reported to decrease the Ac-Smad3 protein expression to inhibit renal fibrosis." (PMID 34177571, 2021). "Erbb4-IR binds to the inhibitory Smad7 and blocks TGF-β/Smad3-induced renal fibrosis, while overexpression of Erbb4-IR may promote fibrosis by downregulating the expression of Smad7." (PMID 34054586, 2021). "Immunohistochemistry, western blotting, and quantitative real-time PCR revealed that, compared with control UUO mice, CRP Tg/Smad3 WT mice developed severe renal fibrosis by increasing both mRNA and protein levels of collagen I, fibronectin, and α-smooth muscle actin (α-SMA)." (PMID 34671208, 2021). "The activation of Smad2 and Smad3 results in aggressive ECM deposition in interstitial and glomerulus that cause interstitial fibrosis and glomerulosclerosis in kidney respectively, while the inhibition of Smad3 phosphorylation retarded renal fibrosis in UUO rats." (PMID 32957963, 2020). "Thus, knockdown of miR-21 restores renal Smad7 levels and blocks both TGF-β/Smad3 and NF-κB signaling, thereby inhibiting progressive renal fibrosis and inflammation in mouse models of obstructive and diabetic nephropathy." (PMID 32258028, 2020). "The cytokine transforming growth factor β (TGF‐β) plays a central role in the development of renal fibrosis by activating multiple downstream signaling pathways, for example, mothers against decapentaplegic homolog 3 (Smad3) and connective tissue growth factor (CTGF) pathways." (PMID 32794631, 2020). "The MMT promotes renal fibrosis, which was reduced in Smad3 knockout mice." (PMID 33298919, 2020). "Collectively, inhibition of Smad3 or Snail1 may be a potential therapeutic target for renal fibrosis." (PMID 32696548, 2020). "Src is the upstream of Smad3, regulating fibroblast proliferation and renal fibrosis." (PMID 32512831, 2020). "TGF-β may specifically regulate renal fibrosis and inflammation via downstream Smad-dependent mechanisms involving Smad3, Smad4, Smad7, and particularly Smad3-dependent non-coding RNAs." (PMID 32258028, 2020). "It has been reported that miR-192 may be a critical downstream mediator of TGF-β/Smad3 signaling in the development of renal fibrosis." (PMID 33603670, 2020). "Other studies have demonstrated that Smad3 mediated TGF-β1-induced renal fibrosis." (PMID 32948751, 2020). "Additionally, administering a specific Smad3 inhibitor early after streptozotocin treatment not only reduced renal fibrosis, it also abrogated EndoMT." (PMID 32268503, 2020). "Furthermore, persistent EGFR activation is critical for mediating sustained activation of the TGF‐β/Smad3 pathway in renal fibrosis." (PMID 32969198, 2020). "Resveratrol, an anti-inflammatory and antioxidant polyphenol, inhibits renal fibrosis via the activation of SIRT1 and deacetylation of SMAD3 in UUO mice, and decreases the renal fibrosis caused by diabetic hyperglycemia activated renal fibroblasts via the inhibition of AMPK/NOX4/ROS signaling." (PMID 33163486, 2020). "In addition, CdCl2 induced renal fibrosis by triggering TGF-β1/SMAD3/α-SMA/collagen signaling within renal cells." (PMID 31022990, 2019).
renal fibrosis (continued). "The beneficial effect of petA may occur through the inhibition of TGF‐β1/Smad3 and NF‐κB signalling, subsequently reducing renal fibrosis and inflammation in UUO kidneys." (PMID 31211499, 2019). "Interestingly, TGF-β1/Smad3 signaling was critical for the transition of bone marrow-derived macrophages into collagen-producing myofibroblasts in a renal fibrosis mouse model of unilateral ureteric obstruction." (PMID 29544542, 2018). "In consonance with our results, Kim and Padanilam found that PARP1 deficiency in a model of Parp1-KO mice attenuated renal fibrosis and inflammation during unilateral ureteral obstruction but TGF-β1/Smad3 signaling pathway remained unchanged in Parp1-KO and WT mice." (PMID 29599129, 2018). "However, a previous study has reported that genetic knockout of Smad3 attenuates not only renal fibrosis but also macrophage infiltration in UUO mice." (PMID 30114247, 2018). "In addition, strategy targeting rebalancing TGF-β/Smad3/Smad7 signaling in vivo has been demonstrated to be effective for reducing renal fibrosis in obstructive nephropathy." (PMID 30524310, 2018). "However, TGF-β1, a profibrotic cytokine causes downregulation of miR29b via TGF-β1/Smad3 pathway and elevates expression levels of collagen-I, III and IV contributing to renal fibrosis in RPTECs." (PMID 30496316, 2018). "MA-35 also has a Smad3 inhibiting effect and therefore may be effective for such renal diseases as well as renal fibrosis." (PMID 28507324, 2017). "Besides, specific inhibitor of Smad3 (SIS3) to inhibit endothelial-myofibroblast transition and renal fibrosis in a type 1 diabetic kidney disease demonstrates a therapeutic potential for kidney disease by targeting Smad3 signaling." (PMID 26997760, 2016). "Smad7 is a negative regulator of TGF-β1/Smad3 signaling, which may reflect its protective role in renal fibrosis." (PMID 27610006, 2016). "Similarly to Smad2, also Smad7, a member of inhibitory group of I-Smads, is a negative regulator of TGF-β1/Smad3 signaling, and a growing number of papers indicate its protective role in renal fibrosis." (PMID 27610006, 2016). "Blockade of NF-κB-driven renal inflammation and TGF-β/Smad3-mediated renal fibrosis by preventing the Smurf2-mediated Smad7 degradation pathway may be mechanisms through which TSF inhibits type 2 DN." (PMID 26807792, 2016). "We also identify that prevention of Smurf2-mediated Smad7 ubiquitin degradation, thereby inhibiting both TGF-β/Smad3-mediated renal fibrosis and NF-κB-dependent renal inflammation may be mechanisms associated with the beneficial effect of TSF on DN." (PMID 26807792, 2016). "Finally, we also found that CRP induced renal fibrosis through a CD32b-Smad3-mTOR pathway because blocking mTOR signaling with rapamycin inhibited CRP-induced CTGF and collagen I expression." (PMID 27221338, 2016). "More significantly, we also found that inhibition of Smurf2-mediated ubiquitin degradation of Smad7 may be a central mechanism by which TSF suppressed both TGF-β/Smad3-mediated renal fibrosis and NF-κB-dependent renal inflammation in the diabetic kidney." (PMID 26807792, 2016). "CRP may promote renal inflammation via the CD32b-NF-κB signaling mechanism, whereas, CRP may enhance renal fibrosis via the CD32b-Smad3-mTOR signaling pathway." (PMID 27221338, 2016). "In addition, TSF treatment also inactivated TGF-β/Smad3 signaling and therefore suppressed renal fibrosis including expressions of fibronectin, collagen I, and collagen IV." (PMID 26807792, 2016). "Several pieces of evidence from our recent study suggest that RSV could decrease proteinuria and serum creatinine, attenuate renal pathological change and the expression of renal fibrosis gene through Sirt1 activation and reduced Smad3 acetylation." (PMID 27129290, 2016). "The TGF-β/Smad3 signalling pathway plays a key role in the development of renal fibrosis." (PMID 26909597, 2016).
renal fibrosis (continued). "This may account for the finding that activation of TGF-β1/Smad3 signaling and renal fibrosis was significantly enhanced in the diabetic kidney of CRPtg-db/db mice." (PMID 27221338, 2016). "In addition, the protection seen in Smad3−/− chimeric mice provides evidence that bone marrow-derived macrophages make a substantial contribution to the development of renal fibrosis via the MMT process that is regulated by TGF-β/Smad3 signaling." (PMID 26684242, 2016). "CRP may promote CD32b- NF-κB signaling to mediate renal inflammation; whereas, CRP may enhance renal fibrosis in T2DN via CD32b-Smad3-mTOR signaling." (PMID 27221338, 2016). "If Smad7 is extensively degraded, Smad3 becomes overactivated and renal fibrosis is enhanced." (PMID 26807792, 2016). "Calcitriol completely inhibited this pro-fibrotic mechanism, suggesting that the actions of vitamin D in renal fibrosis may involve a downregulation of the TGF-β1/Smad3 axis." (PMID 25823676, 2015). "Targeting TGF-β/Smad3 signaling may represent a specific and effective therapy for CKD associated with renal fibrosis." (PMID 25852569, 2015). "TGF-β also down-regulates the expression of miR-29, while miR-29 could inhibit TGF-/Smad3 mediated renal fibrosis only in vitro." (PMID 29861424, 2015). "Furthermore, the authors disclosed that pentoxifylline attenuated renal fibrosis by blocking Smad3/4-activated transcription in a unilateral ureter obstruction model." (PMID 26612282, 2015). "Importantly, we also found that overexpression of Smad7 locally in the kidneys with established chronic AAN was capable of attenuating progressive chronic AAN by inactivating TGF-β/Smad3-medated renal fibrosis and NF-κB-driven renal inflammation." (PMID 25883225, 2015). "Our results suggest that sorafenib may useful for the treatment of renal fibrosis through the suppression of TGF-β/Smad3-induced EMT signaling." (PMID 25679376, 2015). "This suggests that miR-433 may be a critical fibrosis related miRNA in TGF-β/Smad3 driven renal fibrosis." (PMID 29861424, 2015). "As Azin1 promotes polyamine synthesis and polyamine depletion can activate TGF-β signaling by increasing the expression levels of TGF-β1, TβRI, and Smad3, elevation of miR-433 during renal fibrosis forms a positive feedback loop to amplify TGF-β signaling by suppressing Azin1 expression." (PMID 25750628, 2015). "Thus, overexpression of miR-29 and miR-200 or down-regulation of miR-21 and miR-192 is capable of attenuating Smad3-mediated renal fibrosis in various mouse models of chronic kidney diseases (CKD)." (PMID 25852569, 2015). "Furthermore, recent studies demonstrated that Smad3 mediates renal fibrosis by down-regulating miR-29 and miR-200 but up-regulating miR-21 and miR-192." (PMID 25852569, 2015). "In addition, polyamine depletion activates TGF-βsignaling and our laboratory recently demonstrated that depletion of cellular polyamine levels by targeting Azin1 with a Smad3-dependent miR-433 exaggerates TGF-β-induced renal fibrosis." (PMID 25750628, 2015). "Inhibition of TGF-β/Smad3 and NF-κB signaling pathways may be mechanisms by which Smad7 attenuates AA-induced renal fibrosis and inflammation." (PMID 25883225, 2015). "Furthermore, miR-29 acted as a downstream inhibitor and therapeutic miR for TGF-β1/Smad3-mediated renal fibrosis." (PMID 26305546, 2015). "Smad3 is a critical downstream mediator responsible for renal fibrosis that has been shown to function in the diabetes-induced up-regulation of fibronectin and α3 (IV) collagen, and that may play a critical role in the early phase of DN." (PMID 24885228, 2014). "Because it has been reported that microRNA-21 is a downstream of TGF-β/Smad3 and plays a pathogenic role in renal fibrosis in both diabetic and non-diabetic kidney diseases." (PMID 24646636, 2014). "CHYS attenuates DN by blocking TGF-β/Smad3-mediated renal fibrosis." (PMID 24646636, 2014).